INS (insulin)
Diseases named in the same sentence as INS in open-access papers (continued):
Sharing a sentence is not in itself a finding about the gene and the disease.
dementia (continued). "In the present study, in opposition to leptin and adiponectin (both in dementia and non-demented elderly controls) we did not observe any correlation between resistin and metabolic parameters i.e. BMI, fasting glucose, insulin and HOMA-IR index." (PMID 28421328, 2017). "Fewer than 5 studies focused on the relationship between abnormal insulin levels and nonpsychotic dementia types other than AD and VD." (PMID 29445549, 2017). "A random-effects meta-analysis was performed, and the results showed that the nonpsychotic dementia patients had significantly higher insulin levels than were observed in the HCs (Hedges' g = 0.853, 95% CI = 0.579 to 1.127, and P = 0.000)." (PMID 29445549, 2017). "A random-effects meta-analysis showed that insulin levels were not significantly different between the nonpsychotic dementia patients and HCs (Hedges' g = 0.194, 95% CI = −0.251 to 0.640, and P = 0.393)." (PMID 29445549, 2017). "Third, we compared the levels of insulin (mU/L) in the peripheral blood between patients with nonpsychotic dementia and HCs." (PMID 29445549, 2017). "A random-effects meta-analysis was performed, and the results showed that the middle and heavy nonpsychotic dementia patients had significantly higher insulin levels than were observed in the HCs (Hedges' g = 2.379, 95% CI = 1.007 to 3.752, and P = 0.001)." (PMID 29445549, 2017). "Many studies have focused on the changes that occur in the Pi3k-Akt insulin signaling pathway in nonpsychotic dementia patients." (PMID 29445549, 2017). "Recently, abnormal insulin levels were shown to be an important factor that influences the occurrence of nonpsychotic dementia." (PMID 29445549, 2017). "Experimental or observational studies that enrolled people with nonpsychotic dementia or abnormal insulin levels in which insulin levels or MMSE scores (events in nonpsychotic dementia) were the outcome measures." (PMID 29445549, 2017). "A random-effects meta-analysis was performed, and the results showed that the nonpsychotic dementia patients had significantly higher insulin levels than were observed in the HCs (Hedges' g = 0.852, 95% CI = 0.494 to 1.209, and P = 0.000)." (PMID 29445549, 2017). "The high insulin subjects had significantly lower MMSEs and nonpsychotic dementia events than were observed in the HCs, and blood insulin levels were significantly higher in nonpsychotic dementia patients than in HCs." (PMID 29445549, 2017). "MH insulin levels (but not L levels) were significantly higher in nonpsychotic dementia patients than in HC subjects, and low heterogeneity was found in the L group analysis." (PMID 29445549, 2017). "Insulin levels increased in the nonpsychotic dementia patients, and cognitive function scores decreased in subjects with high insulin levels." (PMID 29445549, 2017). "Second, we compared the MMSE scores and the incidence of nonpsychotic dementia between patients with abnormal levels of insulin and HCs." (PMID 29445549, 2017). "Overall, CSF insulin levels were lower in nonpsychotic dementia patients (enrolled sample number < 10, more experimental data are needed to support this finding)." (PMID 29445549, 2017). "A random-effects meta-analysis was performed, and the results showed that mild nonpsychotic dementia patients had significantly higher insulin levels than were observed in the HCs (Hedges' g = 0.520, 95% CI = 0.284 to 0.757, and P = 0.000)." (PMID 29445549, 2017). "Eight sets of data obtained from 4 studies support the finding that there is a relationship between CSF insulin levels and the severity of nonpsychotic dementia." (PMID 29445549, 2017). "We explored the relationship between insulin levels and the occurrence of nonpsychotic dementia from three different perspectives." (PMID 29445549, 2017).
dementia (continued). "A random-effects meta-analysis was performed, and the results showed that the nonpsychotic dementia patients had significantly lower CSF insulin levels than were observed in the HCs (Hedges' g = 1.196, 95% CI = 0.238 to 2.514, and P = 0.014)." (PMID 29445549, 2017). "First, we compared the insulin levels (mU/L) in the CSF between patients with nonpsychotic dementia and HCs." (PMID 29445549, 2017). "Because the number of studies that included a CSF group, a VD group, an MCI patient group, an L group, and an MH group was small, our results only reveal that there is a correlation between insulin levels and nonpsychotic dementia in these groups." (PMID 29445549, 2017). "Compared with the plasma group, the serum group had significantly greater ESs in the nonpsychotic dementia patients with higher insulin levels." (PMID 29445549, 2017). "Furthermore, brain insulin signaling is deregulated in the brains of individuals with AD32, 33, in which progressive cognitive impairment and dementia are the major clinical symptoms." (PMID 26879001, 2016). "Encouraging results obtained from intranasal insulin therapy in aged adults as well as in AD and MCI patients support the idea that insulin signaling is disrupted during normal aging and in clinical cases of dementia." (PMID 25394486, 2014). "The consumption of “pastries and cookies” showed an increasing correlation with serum insulin levels (r = 0.36, p = 0.018), and the consumption of “soups” showed an inverse correlation with total cholesterol levels (r = −0.36, p = 0.02) in patients with MCI and dementia." (PMID 39166127, 2024). "Insulin is the last resort medication when antidiabetics do not work efficiently enough anymore, and it is important to look at its impact on the development of dementia." (PMID 38152822, 2023). "Another study found that the proportion of elderly patients with an A1c < 7% who received a prescription for sulfonylurea, insulin or combined insulin and sulfonylurea therapies was 35.2%, 24.2%, and 16.3% respectively and was as prevalent in those with dementia as in those without." (PMID 36163181, 2022). "In addition, insulin signaling pathways also play a crucial role in MCI and dementia." (PMID 36570466, 2022). "Therefore, due to its likely protective roles, including insulin-sensitizing and its anti-inflammatory and anti-oxidative effects, ADPN could represent a possibility for preventing and treating dementia." (PMID 32188008, 2020). "We hypothesized that rather than Aβ modulation, the strategy to stimulate insulin signaling with high specificity in the brain can improve progressive cognitive dysfunction in severe dementia." (PMID 30518944, 2018). "Hence, the significance of insulin levels to the etiology of nonpsychotic dementia etiology was not fully known." (PMID 29445549, 2017). "In addition, both in dementia and non-demented elderly controls, we observed a high negative correlation between adiponectin and metabolic parameters i.e. BMI, fasting glucose, insulin and HOMA-IR index." (PMID 28421328, 2017). "Second, because the severity of nonpsychotic dementia increased with the ages of the affected patients, insulin levels may simply increase with age and may not be a key factor in the pathology of nonpsychotic dementia." (PMID 29445549, 2017). "Furthermore, exogenous insulin interventions or treatments have been shown to alleviate nonpsychotic dementia symptoms in patients with insulin resistance and improve their Mini-Mental State Examination (MMSE) scores." (PMID 29445549, 2017). "Whether circulating levels of insulin are altered in nonpsychotic dementia patients has been controversial for a long time." (PMID 29445549, 2017). "Moreover, the nonpsychotic dementia group and AD group showed slight publication biases and had the following Egger's test values: for insulin, t = 3.26, d.f. = 50, and P = 0.001; and for AD, t = 2.399, d.f. = 32, and P = 0.011 (Additional File10)." (PMID 29445549, 2017).
dementia (continued). "However, other studies have demonstrated that insulin levels are negatively correlated with nonpsychotic dementia." (PMID 29445549, 2017). "Accordingly, treatment with intranasal insulin, which results in direct insulin transport from the nasal cavity to the CNS via intraneuronal and extraneuronal pathways, improves cognition in patients with and without dementia." (PMID 28400713, 2017). "A subgroup analysis showed that serum insulin levels (as opposed to plasma levels) were significantly higher in nonpsychotic dementia patients than in HC subjects and that VD insulin levels (as opposed to AD levels) were significantly higher in nonpsychotic dementia patients than in HC subjects." (PMID 29445549, 2017). "Our comprehensive results indicate that blood insulin levels may increase in patients with nonpsychotic dementia." (PMID 29445549, 2017). "Our results show that CSF insulin levels are lower in patients with nonpsychotic dementia than in HCs, while insulin levels in the peripheral blood may be higher." (PMID 29445549, 2017). "Whether it be PeaPure® for pain management or Avandia® for insulin sensitization, PPAR agonists have clear, medical value which might yet be expanded if clinical trials using these agonists to treat conditions from cancer to dementia prove fruitful." (PMID 25191225, 2014). "The implication of such hormone signals in the pathology of dementia is supported by the evidence that phosphorylation of MAPT, which leads to neurofibrillary tangle formation and ultimately neurodegeneration, is regulated by the signaling effects of insulin and estradiol." (PMID 23885764, 2013). "It is also noteworthy that FoxO-mediated transcription is not the only mediator of the insulin and insulin-like growth factor-1 cascade, and that several factors might therefore be involved in the pathogenesis of dementia." (PMID 22761616, 2012). "However, whether insulin therapy improves cognitive function or dementia in PD patients has not yet been assessed." (PMID 29515352, 2018). "Moreover, both in all dementia patients and non-demented elderly controls, we confirmed a high positive correlation between leptin and selected metabolic parameters i.e. BMI, fasting glucose, insulin and HOMA-IR index previously stated in elderly subjects." (PMID 28421328, 2017). "Therefore, it is important to determine whether insulin plays a specific role in nonpsychotic dementia." (PMID 29445549, 2017). "Compared to individuals without incident dementia, individuals with incident dementia tended to be older, male, APOE ε4 carriers, and smokers; were more likely to take cholesterol-lowering medications, and insulin." (PMID 35927253, 2022). "Therefore it seems that the identification of astrocytes as an insulin and IGF-I source in the brain would allow us to better understand the importance of these factors in brain physiology, and it could also point to a new therapeutic target for dementia and age-related cognitive disorders." (PMID 32832007, 2020). "Hence, as the study size increased, the trend toward an increase in serum insulin levels in the MCI patients might reach significance, and insulin levels are more likely to vary with the severity of the nonpsychotic dementia." (PMID 29445549, 2017). "Thus, we next sought to determine whether there are differences in blood insulin levels between HCs and patients with MCI, mild (or light) nonpsychotic dementia (L, MMSE scores ≥ 16) and moderate or heavy nonpsychotic dementia (MH, MMSE scores < 16)." (PMID 29445549, 2017).
diabetic ketoacidosis (350 papers, 2008 to 2026). The metabolic condition resulted from uncontrolled diabetes mellitus, in which the shift of acid-base status of the body toward the acid side because of loss of base or retention of acids other than carbonic acid is accompanied by the accumulation of ketone bodies in body tissues and fluids. "Prior knowledge of diabetic ketoacidosis, access to insulin pumps, medicalguidance, and better glycemic control were associated with a greaterunderstanding of diabetic ketoacidosis." (PMID 40893024, 2025). "Insulin pump therapy was associated with lower all‐cause mortality and risk of diabetic ketoacidosis, but an increased risk of diabetic retinopathy compared with MDI." (PMID 40390300, 2025). "Euglycemic diabetic ketoacidosis is primarily caused by changes in insulin/glucagon ratio, increased ketogenesis, glycosuria, and the ketone reabsorption effect of SGLT2i." (PMID 40429346, 2025). "Inadequate insulin leads to acute metabolic crises; even short lapses can cause life-threatening diabetic ketoacidosis (DKA)." (PMID 40938912, 2025). "Diagnostic tests confirmed diabetic ketoacidosis, and while he was initially treated following the institutional protocol, he continued to require insulin therapy indefinitely." (PMID 39726058, 2024). "Diabetic ketoacidosis is most frequently caused by a decrease in insulin activity or an increase in insulin demand." (PMID 38674903, 2024). "Diabetic ketoacidosis is a serious and potentially life-threatening condition that occurs when an insulin deficit causes lipolysis and the formation of ketone bodies and acidosis in the blood." (PMID 36741600, 2023). "While insulin therapy and patient education have improved, diabetic ketoacidosis remains a common cause of hospitalization and is associated with notable morbidity and mortality." (PMID 37363479, 2023). "The presence of at least one anti-islet antibody (GADA or IA2) in obese children with T2D was associated with younger age, lower insulin secretion, higher HbA1c, and a higher incidence of diabetic ketoacidosis at diagnosis." (PMID 36589801, 2022). "Nonetheless, risk of diabetic ketoacidosis with SGLT2i is found to be associated with rapid lowering or cessation of exogenous insulin." (PMID 36224542, 2022). "Is a subcutaneous insulin protocol implemented at a hospital level associated with use of intensive care and other outcomes among adults with diabetic ketoacidosis?" (PMID 35389497, 2022). "Diabetic ketoacidosis is a serious and rare complication caused by low insulin levels and high glucagon levels." (PMID 35337085, 2022). "We limited the insulin deprivation duration for participant safety and due to risk for diabetic ketoacidosis, particularly in the pediatric group, in which even after 6 hours, some adolescents had substantial metabolic derangements." (PMID 33561011, 2021). "For example, diabetic ketoacidosis is a life-threatening complication of T1DM caused by a shortage of insulin that demands insulin injections and blood glucose monitor." (PMID 32719778, 2020). "With insulin pump therapy, there has always been a concern for increased risk of diabetic ketoacidosis (DKA), a life-threatening complication of T1DM." (PMID 30875898, 2019). "This condition requires lifelong management, including insulin therapy, continuous glucose monitoring, dietary adjustments, and regular medical follow-up to prevent acute complications like diabetic ketoacidosis (DKA) and to mitigate the risk of long-term complications." (PMID 41295485, 2025). "Thus, while classic diabetic ketoacidosis arises from insulin deficiency, euglycemic diabetic ketoacidosis suppresses insulin activity." (PMID 39781139, 2024). "Furthermore, it should be considered that diabetic ketoacidosis is caused by low levels of insulin and that the administration of intravenous insulin is frequently used to resolve this adverse event." (PMID 35337085, 2022).
diabetic ketoacidosis (continued). "In this case, the persistent and initially increasing hyperlactatemia in the ICU despite continuous insulin therapy might have multiple causes including diabetic ketoacidosis and a relative hypovolemic state related to dehydration." (PMID 35655318, 2022). "Herein, we highlight the challenges in making this diagnosis and present Sub-Saharan Africa's first experience with therapeutic plasma exchange in the management of hypertriglyceridemic pancreatitis associated with diabetic ketoacidosis, which was initially refractory to insulin infusion alone." (PMID 36514570, 2022). "Taking into account the lack of long-acting or intermediate insulin depot, there is a risk of ketonemia and diabetic ketoacidosis caused predominantly by the pump failure, battery failure, dislodgement or occlusion of the infusion set, or empty insulin reservoir." (PMID 36422210, 2022). "Diabetic ketoacidosis is associated with reduced level of functional insulin in the body." (PMID 33154858, 2020). "Moreover, diabetic ketoacidosis, which is caused by insulin hyposecretion, often occurs in patients with type I diabetes, but also rapidly (within 6 months after treatment with olanzapine) affects patients with no diabetic symptoms before medication." (PMID 33198886, 2020). "Interestingly, although patients with FCPD are insulin deficient and require life-long insulin therapy, they rarely develop diabetic ketoacidosis (DKA)." (PMID 28702252, 2016). "However recent data has shown that SGLT2 inhibitors, particularly empagliflozin, carry the risk of inducing euglycemic diabetic ketoacidosis under certain circumstances such as acute illness, and decreased carbohydrate intake, decrease in dose, or discontinuation of insulin." (PMID 33889468, 2021). "Diabetic ketoacidosis (DKA) is a severe diabetic emergency usually triggered by an infection or missed insulin doses." (PMID 41674770, 2026). "Although several studies have shown potential benefits of KD—such as reduced glucose variability and lower insulin needs—its safety remains a major concern, particularly regarding diabetic ketoacidosis (DKA)." (PMID 41149081, 2025). "There was one patient with the INS variant, two with the ABCC8 variant and one with the HNF1B variant who had diabetic ketoacidosis (DKA) at initial diagnosis." (PMID 40303944, 2025). "Patients presenting with diabetic ketoacidosis should promptly receive intravenous insulin in combination with fluid and electrolytes, while for milder presentations subcutaneous insulin injections are preferred." (PMID 41010821, 2025). "On the third hospital day, upon resolution of diabetic ketoacidosis, he was switched from continuous insulin infusion to multiple daily subcutaneous injections of insulin." (PMID 40662006, 2025). "The reduction in T1DM mortality likely stems from advancements in insulin therapy, continuous glucose monitoring, and structured patient education, which have improved glycemic control and reduced acute complications like diabetic ketoacidosis." (PMID 40666058, 2025). "The patient presented with diabetic ketoacidosis and demonstrated rapid insulin secretory recovery, allowing early discontinuation of insulin." (PMID 39925547, 2025). "Despite sulfonylurea therapy, she required insulin and experienced recurrent diabetic ketoacidosis (DKA) due to poor adherence." (PMID 41367451, 2025). "Biochemical profiles and outcomes of diabetic ketoacidosis (DKA) episodes with fixed rate intravenous insulin infusion (FRIII) rate reduction by 50% initial rate when blood glucose <14 mmol/L during DKA." (PMID 39928758, 2025). "She remained hyperglycemic despite being on a continuous intravenous insulin infusion running at 10 units/hour and later developed diabetic ketoacidosis on 18 units/hour of insulin." (PMID 40860576, 2025). "Why should we use insulin in small doses by intravenous infusion in an emergency as diabetic ketoacidosis?" (PMID 38997722, 2024).